JMJD6 (jumonji domain containing 6, arginine demethylase and lysine hydroxylase)
Description:
Dioxygenase that can both act as a arginine demethylase and a lysyl-hydroxylase. Acts as a lysyl-hydroxylase that catalyzes 5-hydroxylation on specific lysine residues of target proteins such as U2AF2/U2AF65 and LUC7L2. Regulates RNA splicing by mediating 5-hydroxylation of U2AF2/U2AF65, affecting the pre-mRNA splicing activity of U2AF2/U2AF65. Hydroxylates its own N-terminus, which is required for homooligomerization. Plays a role in the regulation of nucleolar liquid-liquid phase separation (LLPS) by post-translationally modifying LIAT1 at its lysine-rich domain which inhibits LIAT1 nucleolar targeting (By similarity). In addition to peptidyl-lysine 5-dioxygenase activity, may act as an RNA hydroxylase, as suggested by its ability to bind single strand RNA. Also acts as an arginine demethylase which preferentially demethylates asymmetric dimethylation. Demethylates histone H3 at 'Arg-2' (H3R2me) and histone H4 at 'Arg-3' (H4R3me), including mono-, symmetric di- and asymmetric dimethylated forms, thereby playing a role in histone code. However, histone arginine demethylation may not constitute the primary activity in vivo. In collaboration with BRD4, interacts with the positive transcription elongation factor b (P-TEFb) complex in its active form to regulate polymerase II promoter-proximal pause release for transcriptional activation of a large cohort of genes. On distal enhancers, so called anti-pause enhancers, demethylates both histone H4R3me2 and the methyl cap of 7SKsnRNA leading to the dismissal of the 7SKsnRNA:HEXIM1 inhibitor complex. After removal of repressive marks, the complex BRD4:JMJD6 attract and retain the P-TEFb complex on chromatin, leading to its activation, promoter-proximal polymerase II pause release, and transcriptional activation. Demethylates other arginine methylated-proteins such as ESR1. Has no histone lysine demethylase activity. Required for differentiation of multiple organs during embryogenesis. Acts as a key regulator of hematopoietic differentiation: required for angiogenic sprouting by regulating the pre-mRNA splicing activity of U2AF2/U2AF65 (By similarity). Seems to be necessary for the regulation of macrophage cytokine responses.
Synonyms: KIAA0585; PSR; PTDSR; PTDSR1
Tractability: Small molecule: a structure with a bound ligand is known; a high-quality ligand is known; it has a binding pocket of medium quality. Antibody: its Gene Ontology location is reachable by antibodies, with medium confidence. PROTAC: ubiquitination databases record sites on it; its protein half-life has been measured; a small molecule that binds it is known.
Target class: Enzyme; Oxidoreductase
Gene: Protein-coding gene on chromosome 17 (76,712,832 to 76,726,784, reverse strand). Ensembl gene ENSG00000070495.
Subcellular location: Nucleus, nucleoplasm; Nucleus, nucleolus; Cytoplasm
Subcellular location (Human Protein Atlas): Nucleoplasm
Pathways (Reactome):
Chromatin organization: HDMs demethylate histones
Metabolism of proteins: Protein hydroxylation
Gene Ontology:
Molecular function: histone demethylase activity; histone H3R2 demethylase activity; histone H4R3 demethylase activity; identical protein binding; iron ion binding; oxidative RNA demethylase activity; P-TEFb complex binding; peptidyl-lysine 5-dioxygenase activity; protein binding; protein demethylase activity; single-stranded RNA binding; transcription regulator activator activity; RNA binding; signaling receptor activity
Biological process: chromatin remodeling; oxidative RNA demethylation; peptidyl-lysine hydroxylation to 5-hydroxy-L-lysine; positive regulation of DNA-templated transcription; positive regulation of transcription by RNA polymerase II; protein homooligomerization; regulation of mRNA splicing, via spliceosome; membraneless organelle assembly; negative regulation of protein homooligomerization; peptidyl-lysine hydroxylation; phagocytosis; sprouting angiogenesis
Cellular component: cytoplasm; nucleolus; nucleoplasm; nucleus; cytosol; plasma membrane; ribonucleoprotein complex
Genetic constraint (gnomAD): Loss-of-function variants: 17 observed, 48.1 expected, observed/expected ratio (o/e) 0.35, 90% interval 0.24 to 0.53. The upper end of that interval is the gene's LOEUF score, 0.53, which puts it in group 2 of 6, group 1 being the genes least tolerant of losing a copy. Missense variants: 470 observed, 540.53 expected, observed/expected ratio (o/e) 0.87, 90% interval 0.81 to 0.94. Synonymous variants: 221 observed, 204.76 expected, observed/expected ratio (o/e) 1.08, 90% interval 0.97 to 1.21.
Homologues: Orthologues: macaque JMJD6 (99% identical), dog JMJD6 (98% identical), guinea pig JMJD6 (98% identical), mouse Jmjd6 (98% identical), pig JMJD6 (98% identical), chimpanzee JMJD6 (97% identical), rabbit JMJD6 (88% identical), zebrafish jmjd6 (85% identical), rat Jmjd6 (85% identical), tropical clawed frog jmjd6 (85% identical), Drosophila melanogaster JMJD6 (66% identical), Caenorhabditis elegans psr-1 (50% identical). Paralogues in human: JMJD4 (22% identical), JMJD8 (17% identical).
Diseases named in the same sentence as JMJD6 in open-access papers:
JMJD6 is named in the same sentence as 89 diseases in open-access papers, as found by Europe PMC text mining. Sharing a sentence is not in itself a finding about the gene and the disease. The quoted sentences say what the papers report.
breast cancer (24 papers, 2010 to 2025). A primary or metastatic malignant neoplasm involving the breast. "Our earlier paper indicated that high expression of JMJD6 in ER+ breast cancers was associated with poor survival despite treatment of these women with endocrine therapy (Tam)." (PMID 36419768, 2022). "High expression of Jumonji domain containing protein 6 (JMJD6) is strongly associated with poor prognosis in estrogen receptor positive (ER+) breast cancer." (PMID 36419768, 2022). "This is consistent with a previous report that demonstrated that high JMJD6 was associated with a worse prognosis in ER+ breast cancer." (PMID 27081402, 2016). "Importantly, we demonstrate that co-expression of high levels of JMJD6 and Myc is associated with poor prognosis for human ER+ breast cancer patients." (PMID 27081402, 2016). "Based on our observations that high expression of JMJD6 associated with high histological grade and with aggressiveness of breast cancer, we hypothesised that JMJD6 might have a role in the regulation of growth and migration of breast cancer cells." (PMID 25951181, 2015). "It was recently reported that JMJD6 is a top candidate gene robustly associated with poor differentiation and patient survival in breast cancer based on the analysis of an integrated “Super Cohort” (SC) of 15 individual Affymetrix array datasets comprising 2,116 breast cancer patients." (PMID 24667498, 2014). "JMJD6 hijacked the E2-ER axis of proliferation by inducing E2F regulated genes and G2-M transitions to sustain breast cancer growth." (PMID 40855961, 2025). "A JMJD6 interaction region (JIR) that positively regulated HOTAIR expression in breast cancer cell lines was also identified in the same study." (PMID 40855961, 2025). "We have earlier identified JMJD6 as a poor prognostic factor in breast cancer and shown its positive impact on cell proliferation and motility." (PMID 40855961, 2025). "JMJD6 is a member of the Jumonji C-domain-containing family and has emerged as a promising target for various diseases, including breast cancer, prostate cancer, and Alzheimer’s disease." (PMID 38732153, 2024). "Studies have shown that JMJD6, as an oncogene, is involved in the pathogenesis of many cancers, including oral cancer, colorectal cancer, breast cancer, lung cancer, and hepatocellular carcinoma etc., and is closely related to the poor prognosis of patients." (PMID 37488513, 2023). "A recent report provided new insights to the mechanisms of JMJD6-mediated breast cancer progression." (PMID 37567973, 2023). "EZH2 and JMJD6 gene profiles overlap in breast cancers, with EZH2 co-regulating a unique gene box in both ER+ and ER− cells." (PMID 37069494, 2023). "For instance, JMJD6 has been identified as a predicting marker for tumor response to tamoxifen endocrine therapy in breast cancer patients." (PMID 37567973, 2023). "JMJD6 appears to have functions beyond that of promoting ER target gene expression in ER+ breast cancer." (PMID 36419768, 2022). "JMJD6 is one of the highly expressed genes in breast cancer and yet its role in breast cancer is two-sided." (PMID 35359945, 2022). "Recently, a small molecule inhibitor of JMJD6 (iJMJD6) has been tested in cell lines and patient derived xenograft systems and found to oppose cancer cell growth and progression of ER+ breast cancer." (PMID 36419768, 2022). "In this regard, JMJD6 is essential for estrogen/ERα-evoked cell growth and tumorigenesis of breast cancer." (PMID 35359945, 2022). "Among the members of family, JMJD6 was reported to be tumorigenic factor which involves in various kinds of cancers such as prostate cancer, breast cancer, melanoma, colon cancer, and lung cancer." (PMID 34980950, 2021). "Several studies have implicated JMJD6 in different types of cancer such as oral squamous cell carcinoma (OSCC), colon cancer, adenocarcinoma of the lung and breast cancer." (PMID 30319972, 2018).
breast cancer (continued). "JMJD6’s contribution to control of apoptosis has also described in mouse mammary tumor models that mimic human breast cancer." (PMID 28360925, 2017). "We report in the current study that JMJD6 is up-regulated in a variety of cancers, including melanoma, thyroid cancer, ovarian cancer, breast cancer, prostate cancer, lung adenocarcinomas, liver cancer, and colorectal cancer." (PMID 29187213, 2017). "Functional links between Jmjd6 and breast cancer are particularly interesting as deregulation of splicing factors and defects in the crosstalk of the splicing network have been proposed to contribute toward cancer development." (PMID 28360925, 2017). "The analysis revealed that the mRNA level of JMJD6 was up-regulated in a variety of cancers, including thyroid cancer, ovarian cancer, breast cancer, prostate cancer, lung adenocarcinomas, liver cancer, colorectal cancer and melanoma." (PMID 29187213, 2017). "JMJD6 has been reported to play an important role in breast cancer and lung adenocarcinomas, and our previous study indicates that JMJD6 is critically involved in colon carcinogenesis." (PMID 29187213, 2017). "The studies from the same group confirmed that JMJD6 is a marker of poor prognosis in breast cancer." (PMID 28587176, 2017). "Bioinformatics analyses of human breast cancer tumors revealed a significant decrease in survival of patients with ER+ tumors when Myc and JMJD6 were highly expressed together as compared to high Myc expression alone." (PMID 27081402, 2016). "We sought to determine to what extent established mammary tumors remain dependent on JMJD6 expression for tumor maintenance and an aggressive phenotype." (PMID 27081402, 2016). "Our studies have revealed important cooperativity between JMJD6 and the Myc proto-oncogene and possibly other types of oncogene-driven breast cancers." (PMID 27081402, 2016). "As arginine methylation is known to be involved in tumourigenesis, we wanted to assess the involvement of the arginine demethylase JMJD6 in breast cancer." (PMID 25951181, 2015). "In addition to translocating ER, JMJD6 is recruited to ER binding sites and is required for oestrogen-induced gene transcription in breast cancer cells." (PMID 40855961, 2025). "To test this idea and explore the functional differences between the two possible isoforms of JMJD6, we overexpressed short or long isoforms of GFP-tagged JMJD6 in the MCF7 breast cancer cell line and assessed their effects on colony formation and cell migration." (PMID 39349823, 2024). "We propose that JMJD6 levels may perform well as a valuable marker to determine response to endocrine therapy and the use of iJMJD6 as a viable therapeutic strategy to treat ER+ breast cancers involving high expression of JMJD6." (PMID 36419768, 2022). "Collectively, based on all these observations, it is possible that increased expression of JMJD6 in breast cancer cells may result in lower response to endocrine treatment, particularly, Tam therapy." (PMID 36419768, 2022). "Based on these data, we propose that JMJD6 may be involved in predisposing cells to Tam insensitivity by decreasing ER, increasing RET expression and total ERK1 levels in ER+ breast cancer cells." (PMID 36419768, 2022). "Data from some studies suggested that the role of JMJD6 in breast cancer depends upon ER status." (PMID 35359945, 2022). "Zeste homologous enhancer 2 (EZH2) may be another chaperone co-regulating gene involved in JMJD6-mediated breast cancer progression." (PMID 35359945, 2022). "In addition, high expression of JMJD6 was an indicator of unfavorable prognosis in ER+ breast cancer." (PMID 36419768, 2022).
breast cancer (continued). "Previous studies have indicated that JMJD6 overexpression may result in poor prognosis for multiple cancers, such as neuroblastoma, breast cancer, and liver cancer." (PMID 33634984, 2021). "Meanwhile, a recent study reported that JMJD6 promotes EMT in breast cancer." (PMID 29187213, 2017). "In addition to cancer of other organs, there is a link between the disease progression and JMJD6 expression in breast cancer cells." (PMID 28587176, 2017). "Thus, in breast cancer, JMJD6 serves as a driver of cell proliferation and motility and an indicator of poor prognosis." (PMID 28587176, 2017). "Jmjd6 may also intersect with estrogen receptor signaling in breast cancer, through regulated methylation of the estrogen receptor α (ERα)." (PMID 28360925, 2017). "In addition, analysis of a large cohort of breast cancer patients (more than 2000) revealed that high JMJD6 expression in human breast cancer with high Myc results in a lower overall survival presumably due to a higher metastatic burden." (PMID 27081402, 2016). "We determined that high JMJD6 expression is associated with a poor prognosis for ER-positive breast cancer patients and not for ER-negative breast cancer, consistent with a previous report analyzing JMJD6 expression as a biomarker for poor prognosis in ER+ breast cancer." (PMID 27081402, 2016). "Further work will be necessary to determine whether JMJD6 activity could be deregulated in breast cancer." (PMID 25951181, 2015). "Indeed, knock-down of JMJD6 increased several features of breast cancer including proliferation, migration, colony formation and tumour engraftment." (PMID 25951181, 2015). "Notably, previous works have reported a significant upregulation of JMJD6 in breast cancer tissues, and specific small molecule inhibitors targeting JMJD6 have exhibited a reduction in the proliferative capacity of breast cancer cells both in vitro and in vivo." (PMID 39210450, 2024). "Considering previous reports on the correlation between JMJD6 and cancers, as well as the link between inflammation and cancers, we conducted further investigations using serum samples from patients with esophageal cancer (EC), gastric cancer (GC), lung cancer (LC), and mammary cancer (MC)." (PMID 38732153, 2024). "Although JMJD6 displays anti-tumoral properties in cell lines, its expression in breast tumours may be a marker of poor prognosis, suggesting that its function could be altered in breast cancer." (PMID 25951181, 2015). "We have shown that JMJD6 and EZH2 are almost always co-expressed in breast cancer cells and regulate E2F and DREAM target genes." (PMID 36419768, 2022). "In addition, the mechanism of JMJD6 may differ in distinct subtypes of breast cancer." (PMID 35359945, 2022). "To assess the potential role of JMJD6 on breast cancer progression, we generated MCF-7 cell lines stably expressing shRNAs against JMJD6 (shJMJD6) or a control sequence (shCtr)." (PMID 25951181, 2015). "The 7 angiogenesis genes present in the list were also predominantly down-regulated (e.g. NRP1, JMJD6, CYR61, FGFR1) and again the impact of these genes on the carcinogenesis of breast cancer cells has been described." (PMID 21062462, 2010). "JMJD6 inhibitor has been used to regress tumours in preclinical mouse models and several efforts are being made to design YBX1 inhibitors since it promotes breast cancer metastasis." (PMID 40855961, 2025). "JMJD6 overexpression could induces EMT, and greatly enhances tumor metastasis in neuroblastoma and breast cancer." (PMID 37488513, 2023).
breast cancer (continued). "In ER+ patient samples from TCGA breast cancer data, JMJD6 and ESR1 showed a trend towards negative correlation (Spearman, r2 = -0.23)." (PMID 36419768, 2022). "Though JMJD6 has been identified as an independent marker for poor prognosis in various cancers—such as lung adenocarcinoma, breast cancer, and colon cancer—its role in relation to OSCC is not absolutely clear." (PMID 28587176, 2017). "We therefore investigated whether JMJD6 might enhance migration, invasion, and metastases of MMTV-Myc mammary tumor cells." (PMID 27081402, 2016). "Taken together, the role of JMJD6 in promoting breast cancer progression has been established, although its role in different subtypes of breast cancer may not be identical." (PMID 31961032, 2020). "Consequently, in ER+ tumors, high expression of JMJD6 may allow breast cancer cell proliferation by alternate means, in the absence of E2 or when blockade of the E2-ER axis occurs during endocrine therapy." (PMID 36419768, 2022). "Additionally, since Myc is overexpressed in many breast cancers but not successfully targeted by drugs, inhibiting JMJD6 function may provide a means of inhibiting Myc-dependent tumorigenesis." (PMID 27081402, 2016).